EGFR (epidermal growth factor receptor)
Diseases named in the same sentence as EGFR in open-access papers (continued):
Sharing a sentence is not in itself a finding about the gene and the disease.
breast carcinoma (continued). "Trastuzumab is a monoclonal antibody anti-cancer drug commonly used to treat breast cancer that results in similar downstream effects of EGFR pathway inhibition of impairing cell division and growth." (PMID 35612280, 2022). "It was demonstrated that EGFR-Src-Arg-cortactin pathway mediates functional maturation of invadopodia and breast cancer cell invasion, and the overexpression of the EGF receptor enhanced intravasation." (PMID 35158871, 2022). "Breast cancer cell-derived exosomes transferred activated EGFR to host macrophages, which inhibited their production of type I interferons and antiviral immunity, resulting in compromised innate immunity." (PMID 36499561, 2022). "Results from similar experiments on EGFR (HER1-activated) breast cancer cells such as MDA-468 showed that the effect of drug treatment on EGR4-S levels within this context was still present but not as robust as that observed in HER2+ cell lines." (PMID 35326716, 2022). "We also examined the binding affinity of PEG-SSNs to siRNA and their capability to carry siRNA into the tumour cell and silence the overexpressed EGFR gene with anti-EGFR siRNA in human and murine breast cancer cell lines." (PMID 36412852, 2022). "The main signaling pathways enriched by KEGG included gastric cancer, breast cancer, proteoglycans in cancer, EGFR tyrosine kinase inhibitor resistance, endocrine resistance, hepatocellular carcinoma, MAPK signaling pathway, and hepatitis B." (PMID 36200190, 2022). "After seven days, we delivered non‐targeted and EGFR‐targeted CFSE‐labelled RBCEVs via intrapulmonary administration to the mice bearing metastatic breast cancer." (PMID 35430766, 2022). "Diosgenin increases the phosphorylation level of JNK to inhibit the proliferation of the breast cancer cells with a high expression of human epidermal growth factor receptor and to promote cell apoptosis, possibly by inhibiting Akt and mTOR phosphorylation." (PMID 35698571, 2022). "FAM83A protein expression was directly correlated with EGFR level in both normal and breast cancer tissues." (PMID 35183258, 2022). "designed a low-affinity chimeric receptor CD32A131R to induce the elimination of EGFR-overexpressing breast cancer by crosslinking with cetuximab." (PMID 35935930, 2022). "Significantly more breast cancer with ki67 > 30%, EGFR-positive breast cancer, and CK5/6-positive breast cancers were also seen in BRCA1 mutation carriers." (PMID 35209950, 2022). "The small molecule varlitinib is an EGFR/HER2 (epidermal growth factor receptor) inhibitor that is FDA-approved for the treatment of breast cancer and is known to cross the blood–brain barrier." (PMID 36341365, 2022). "Compared to naïve exosomes, HER2- and EGFR-targeting exosomes demonstrated enhanced delivery to HER2- or EGFR-expressing breast cancer cells in vitro, with approximately 2-fold and ~2–3-fold higher accumulation, respectively." (PMID 35054611, 2022). "STAT1 expression has been reported to be increased in EGFR-positive and HER2-positive breast cancer patients, and relapse-free survival was found to be decreased in high-risk breast cancer patients." (PMID 35781872, 2022). "For example, activating mutations in EGFR are frequent in relapsed lung adenocarcinoma, BRAF is often mutated in melanoma, and PIK3CA is often mutated in various entities, including luminal breast cancer." (PMID 35625984, 2022). "Different studies demonstrated that the EGFR modulates in breast cancer cells the expression of miRNAs involved in cancer progression." (PMID 35406622, 2022). "Epidermal growth factor receptor (EGFR) overexpression has been considered a poor prognostic factor in breast cancer." (PMID 36158981, 2022). "The research used exosomes to deliver miRNA to breast cancer cells targeting the epidermal growth factor receptor (EGFR)." (PMID 36364116, 2022). "CSF1R and EGFR were tyrosine kinase receptors that regulated breast cancer cell growth and proliferation." (PMID 35807438, 2022).
breast carcinoma (continued). "A number of clinical trials have been conducted in breast cancer using TKIs like gefitinib and erlotinib that target the EGFR." (PMID 35908023, 2022). "Examples include rituximab directed against CD20 on malignant B cells, trastuzumab against Her-2/neu on, e.g., subsets of breast cancer cells, and cetuximab, recognizing epidermal growth factor receptor (EGFR) that is overexpressed on many epithelial cancers." (PMID 35884427, 2022). "Progestogen induction of ERK1/2 phosphorylation in breast cancer cells stably transfected with seatrout mPRα is dependent on EGFR transactivation." (PMID 35681480, 2022). "Antitumour miRNAs can be targeted to breast cancer cells expressing the epidermal growth factor receptor (EGFR) by intravenous injections of sEVs." (PMID 36096820, 2022). "EGFR and its activated signaling cascades have notable roles in developing and progressing human breast cancers." (PMID 36412852, 2022). "This together with increased expression of EGFR in those cells explains the strong tumor-suppressing activity of WWOX in breast cancer." (PMID 35290621, 2022). "A significant portion of HER2-positive breast cancer cells co-express EGFR and HER3, and HER2-mediated cell signaling, and cell function is closely related to and impacted by other HER receptors." (PMID 36552857, 2022). "Cetuximab, an EGFR inhibitor, is commonly used as a targeted therapy for patients with breast cancer." (PMID 35963853, 2022). "This complex has been shown to repress epidermal growth factor receptor (EGFR) in breast cancer cell lines, resulting in decreased cell proliferation and motility." (PMID 36686841, 2022). "Annonacin, a potent complex 1 inhibitor, inhibited EGFR activity when used alone, and sensitized multidrug-resistance breast cancer cells to tamoxifen to reduce xenograft tumor burden." (PMID 36700235, 2022). "Intravenous administration of miR-let-7a-loaded Exos to mice had inhibitory effects on tumor development in the presence of breast cancer cells expressing the epidermal growth factor receptor (EGFR)." (PMID 36531952, 2022). "In this study, we demonstrated for the first time that EGFR activation regulates in MSCs the expression of a wide number of miRNAs potentially involved in the cross-talk with breast cancer cells." (PMID 35406622, 2022). "Lapatinib is a new type of human epidermal growth factor receptor 2 (HER2)/EGFR tyrosine kinase inhibitor used for the treatment of HER2-positive breast cancer." (PMID 35153781, 2022). "SFN acts as an HDAC inhibitor in breast cancer cell lines and decreases the protein expression of ER, EGFR, and HER-251." (PMID 35332167, 2022). "Otherwise, localization of EGFR in lipid rafts correlates with EGFR tyrosine kinase inhibitor resistance of breast cancer cell lines which can still mediate Akt signaling in the absence of EGFR kinase activity." (PMID 36439249, 2022). "In prostate and breast cancer cells, palmitoylation occurs at the cysteine residue 797 of the epidermal growth factor receptor (EGFR) residing in mitochondria, which stimulates the activation of EGFR." (PMID 36741694, 2022). "EGFR and HER2 overexpression in breast cancer is associated with resistance to chemotherapy and poor prognosis." (PMID 36297358, 2022). "Previous studies have shown that KIAA1199, an oncogene that is transcriptionally induced by NF-κB proteins, promotes EGFR stability and contributes to the activation of NF-κB/EGFR signaling pathway crosstalk in breast cancer." (PMID 36291177, 2022). "Chrysophanol inhibits cell proliferation by the inhibition of the NF-κB and EGFR/mTOR pathways in colon and breast cancers." (PMID 36676666, 2022). "Overexpression of EGFR in tumour cells has been considered a poor prognostic factor in breast cancer for decades, with rare disagreements." (PMID 36158981, 2022). "Our data suggest that dihydroconiferyl ferulate provides a new compound for breast cancer therapy by targeting EGFR signaling." (PMID 35745583, 2022).
breast carcinoma (continued). "Mechanistically, B6H12 treatment facilitates the expression of exosomal microRNA-7 in breast cancer stem cells, which targets EGFR and KLF4 mRNAs, leading to decreased EGFR, KLF4, and EGF-induced EGFR tyrosine phosphorylation." (PMID 36233088, 2022). "First, we transfected synthetic single-stranded tsRNA targeting EGFR (tsEGFR) into BT549 breast cancer cells in parallel with commercially available double-stranded siRNA against EGFR (siEGFR) and measured the change of EGFR expression by qRT-PCR." (PMID 35048990, 2022). "Several reports point to the role of FAM83A in the regulation of the EGFR pathway in breast cancer cells and in the development of resistance to tyrosine kinase inhibitors (TKIs)." (PMID 35183258, 2022). "Based on these results, we suggest that EGFR-AKT pathway is likely to be the main targets of SH003-DTX combination treatment on breast cancer." (PMID 35572726, 2022). "Activation of the EGFR in MSCs stimulates the production of factors that promote angiogenesis and cell migration in different tumor types, including breast cancer." (PMID 35406622, 2022). "We transduced mouse breast cancer 4T1 cells with lentiviruses carrying the human EGFR expression vectors." (PMID 35430766, 2022). "EGFR overexpression has been reported for all types of breast cancers, particularly triple-negative breast cancer (TNBC) and inflammatory breast cancer (IBC)." (PMID 36412852, 2022). "After the modification with different antibodies toward different biomarkers (ER, EGFR, PR), multicolor imaging of cancer cells and human breast cancer tissues has been completed, confirming their great potential for multiplex imaging in clinical diagnosis." (PMID 35198078, 2022). "Our results finally suggested that the EGFR downregulated in MSCs the expression of miR-23c, thus promoting cancer progression in highly aggressive breast cancer cells." (PMID 35406622, 2022). "Another protein ERα-regulated protein from TGFα-EGFR is PLCB1 which was recently identified as a metastatic breast cancer driver gene." (PMID 35290621, 2022). "Peptide 1 (or GE11) is a dodecapeptide that binds specifically to the epidermal growth factor receptor (EGFR or ErbB1) overexpressed in a number of tumors of epithelial origin including breast cancer, and is being used as a cancer cell-targeting peptide." (PMID 35762636, 2022). "In particular, we found that the EGFR modulates in MSCs the expression of miRNAs involved in breast cancer tumorigenesis, as indicated in the OncoMiR database, progression and response to therapeutic regimens, such as miR-574-3p, miR-342-3p and miR-210-3p." (PMID 35406622, 2022). "In the current study, we used the same lipid nanoprobe technique for postproduction engineering of EVs with THPs targeting PDL1, uPAR, and EGFR expressed in human breast cancer cells." (PMID 35335849, 2022). "EGFR overexpression is reported to be significantly correlated with large tumor size, poor differentiation, and poor clinical outcomes in breast cancer." (PMID 35399416, 2022). "Confirming the role of the EGFR, Shuai and co-workers reported higher internalization of an anti-EGFR monoclonal antibody-conjugated nanoplatform in EGFR-positive human skin squamous cell carcinoma compared to EGFR-negative breast cancer." (PMID 36096856, 2022). "One frequently observed mechanism of endocrine resistance in ERα-positive breast cancer is via increased expression of EGFR or HER2 and this can lead to increased sensitivity to HER inhibitors." (PMID 35441158, 2022). "The most common receptors that are overexpressed in breast cancer cells are part of the epidermal growth factor receptor (EGFR) family of receptor tyrosine kinases." (PMID 36558904, 2022). "HER2 expressed in HER2-enriched and part of luminalB breast cancer is the membrane receptor encoded by the proto-oncogene ERBB2, which is a member of human epidermal growth factor receptor (EGFR/ERB) family of tyrosine kinase receptors." (PMID 35311116, 2022).
breast carcinoma (continued). "In tumor study, IVM has been identified to reverse the chemotherapeutic drugs resistance through EGFR pathway in colorectal and breast cancer." (PMID 36132145, 2022). "U3-1402 is currently under clinical evaluation and has demonstrated antitumor activity and manageable safety profile in breast cancer and EGFR-mutant NSCLC." (PMID 36271429, 2022). "For example, in patients with Her2-positive breast cancer BMs, those with ALK-rearranged or EGFR-mutated NSCLC BMs, and for BRAF V600 E mutated melanoma BMs, targeted therapies with significant intracranial activity are available." (PMID 36605448, 2022). "GEP100/BRAG2 (an ARF6 GEF) expression is higher in invasive breast carcinoma, and its recruitment to EGFR in breast cancer cells results in ARF6 activation and stimulation of cell invasion." (PMID 35143561, 2022). "Herein, we used a safe and simple nano-based delivery system to carry EGFR-siRNA to breast cancer cells." (PMID 35517864, 2022). "In this study, AuNPs (14 nm) were conjugated to 111In-DTPA-EGF to bind epidermal growth factor receptors (EGFR) on breast cancer cells." (PMID 35161087, 2022). "Clinical studies suggest that ER+ve breast cancer patients with overexpression of EGFR have poor survival outcomes and are less likely to benefit from tamoxifen." (PMID 35267559, 2022). "Their study showed that PUFAs inhibited the epidermal growth factor receptor, which in turn reduced the proliferation of breast cancer." (PMID 35614977, 2022). "As with EGFR mutations in advanced NSCLC and PIK3CA mutations in advanced breast cancer, strong concordance has been found between the RAS mutational status of CRC tissue and matching plasma in patients with advanced CRC." (PMID 35055414, 2022). "EGFR has been demonstrated to regulate epithelial tissue development and homeostasis in a variety of types of cancer, including breast cancer, with approximately half of triple-negative breast cancer and inflammatory breast cancer cases overexpressing EGFR." (PMID 36035177, 2022). "Taken together, these data suggest that EGFR mediates Akt inhibitor resistance in luminal breast cancer cells." (PMID 36291790, 2022). "In this study, we further investigate the anti-IGF-I/II IgG1 m708.5 against neuroblastoma and breast cancer cell lines as well as xenografts models alone and in combination with the EGFR inhibitors." (PMID 35399718, 2022). "The EGFR, a transmembrane protein, is involved in the occurrence of several types of cancers, including lung, pancreatic, colorectal, and breast cancers." (PMID 36096856, 2022). "It has also been shown that when nano-SiO2 passes through the cell membranes of breast cancer, it can downregulate EGFR, proto-oncogene c-Src, and signal transducer and activator of STAT3 phosphorylation." (PMID 36559135, 2022). "sEVs modified with the GE11 peptide, which specifically binds to EGFR, have been used to deliver the miRNA let-7a to EGFR-expressing breast cancer tissue." (PMID 36167539, 2022). "For example, miR-145 negatively regulates MUC1 and suppresses invasion and metastasis of breast cancer cells, and miR-145 suppresses proliferation, metastasis, and EMT of colorectal cancer via suppressing the EGFR-associated signaling pathway." (PMID 35847793, 2022). "Given the growing importance of EGFR in the diagnosis and treatment of breast cancer, this approach is certainly valuable." (PMID 35663041, 2022). "Here, we found that N-cadherin was generally upregulated in spheroid breast cancer cells with exogenous expression of EGFR, blockade of EGFR in MDA-MB-231 cells gave rise to an attenuation of N-cadherin." (PMID 35725558, 2022). "In this study, we developed an algorithm to predict EGFR expression in patients with untreated breast cancer based on enhanced MRI and pathologic images." (PMID 35663041, 2022). "DepInfeR correctly detected the dependence of HER2-positive breast cancer cell lines on EGFR (Epidermal Growth Factor Receptor) signaling." (PMID 35994503, 2022).
breast carcinoma (continued). "We previously demonstrated that the epidermal growth factor receptor (EGFR) modulates in mesenchymal stem cells (MSCs) the expression of a number of genes coding for secreted proteins that promote breast cancer progression." (PMID 35406622, 2022). "WT161, an HDAC6 inhibitor, can sensitize luminal breast cancer more effectively than other subtypes by activating the apoptotic protein X-Linked Inhibitor of Apoptosis (XIAP) and downregulating EGFR, HER2, and ERα." (PMID 35453496, 2022). "TP63 increases expression of epidermal growth factor receptor in breast cancer and increases the response of breast cancer to cisplatin." (PMID 35060926, 2022). "One of the mechanisms of TAM resistance in breast cancer cells involves crosstalk with the human EGFR." (PMID 36601474, 2022). "First, FAM83A expression in breast cancer and its correlation with EGFR was evaluated using a large cohort of either normal or cancerous breast tissues." (PMID 35183258, 2022). "These authors also demonstrated the delivery of let-7a to EGFR-expressing breast cancer by an intravenous injection of engineered exosomes in a mouse xenograft model." (PMID 35054611, 2022). "EGFR and human epidermal growth factor receptor-2 (HER2) are overexpressed in approximately 40% and 25% of breast cancers, respectively, and are associated with an aggressive tumor nature and poor prognosis." (PMID 36558904, 2022). "For a proof-of-concept study, multicolor imaging of four cancer biomarkers (HER2, ER, PR, and EGFR) in breast cancer biopsies from three patients has been successfully demonstrated." (PMID 35198078, 2022). "Out of the five designed peptides, ARSHVGYTGAR (E2) was selected as the best peptide to target the EGFR overexpressed breast cancers." (PMID 35160746, 2022). "Another retrospective study conducted on tumor sections from 807 breast cancer patients provided further clinical evidence for the association between HER2 activation and aberrant EGFR expression." (PMID 36291900, 2022). "In ER+ breast cancer cells harboring PIK3CA and PTEN mutations, treatment with a PI3K/mTOR inhibitor resulted in increased RTK-mediated signaling and upregulation of EGFR/ERK/p-BadS112." (PMID 35053443, 2022). "The transmembrane receptor ERBB2 is a tyrosine kinase and belongs to the family of EGFR and plays a prominent role in breast cancer." (PMID 35937803, 2022). "Among them, epidermal growth factor receptor (EGFR) can be used as a new biomarker for monitoring the diagnosis and treatment of breast cancer patients." (PMID 35663041, 2022). "THZ1 has synergistic or additive effects when combined with the EGFR inhibitor erlotinib in breast cancer." (PMID 35406486, 2022). "For example, the c-Src-dependent link between CHKA and EGFR promoted breast cancer cell proliferation and tumorigenesis." (PMID 36147318, 2022). "The synthesized 111In-DTPA-EGF-AuNP conjugate was bound and internalized by EGFR-overexpressing MDA-MB-468 human breast cancer cells, reducing their surviving fraction to 4.4% after 4 h exposure." (PMID 35161087, 2022). "Similar therapeutic effects were also observed with ASO-loaded RBCEVs targeted to an EGFR-positive metastatic breast cancer allograft." (PMID 35547755, 2022). "Epidermal growth factor receptor (EGFR) is strongly linked to cancer progression and it is a promising therapeutic target for breast cancer." (PMID 35565451, 2022). "This overexpression of EGFR in breast cancer as well as other cancer cells including colon and lung cancers made this a potential molecular target for inhibition." (PMID 36146940, 2022). "KSTAR also correctly predicted that a clinically diagnosed HER2-negative PDX model would be responsive to EGFR/HER2 therapy, suggesting that phosphoproteomics combined with KSTAR can offer an orthogonal clinical diagnostic for breast cancer patients." (PMID 35879309, 2022).